ENO1 (enolase 1)
Description:
Enolase that catalyzes the conversion of 2-phosphoglycerate to phosphoenolpyruvate in glycolysis and the reverse reaction in gluconeogenesis. Also involved in various processes such as growth control, hypoxia tolerance and allergic responses. May also function in the intravascular and pericellular fibrinolytic system due to its ability to serve as a receptor and activator of plasminogen on the cell surface of several cell-types such as leukocytes and neurons. Stimulates immunoglobulin production. [Isoform MBP-1]: Binds to the myc promoter and acts as a transcriptional repressor. May be a tumor suppressor.
Synonyms: NNE; ENO1L1; MPB1; PPH; MBP-1; ENO1-IT1; HEL-S-17
Tractability: Small molecule: a structure with a bound ligand is known; a high-quality ligand is known; it has a high-quality binding pocket. Antibody: UniProt places it where antibodies can reach, with high confidence; its Gene Ontology location is reachable by antibodies, with high confidence; the Human Protein Atlas places it where antibodies can reach. PROTAC: UniProt records ubiquitination sites on it; ubiquitination databases record sites on it; its protein half-life has been measured; a small molecule that binds it is known.
Target class: Enzyme
Gene: Protein-coding gene on chromosome 1 (8,860,977 to 8,879,289, reverse strand). Ensembl gene ENSG00000074800.
Subcellular location: Cytoplasm; Cell membrane; Cytoplasm, myofibril, sarcomere, M line; Nucleus (Isoform MBP-1)
Subcellular location (Human Protein Atlas): Cytosol; Plasma membrane
Pathways (Reactome):
Metabolism: Gluconeogenesis; Glycolysis
Disease: Manipulation of host energy metabolism
Gene Ontology:
Molecular function: cadherin binding; DNA-binding transcription repressor activity, RNA polymerase II-specific; GTPase binding; phosphopyruvate hydratase activity; protein binding; protein homodimerization activity; RNA binding; RNA polymerase II transcription regulatory region sequence-specific DNA binding; transcription corepressor activity; transcription corepressor binding; magnesium ion binding
Biological process: canonical glycolysis; negative regulation of cell growth; negative regulation of DNA-templated transcription; negative regulation of hypoxia-induced intrinsic apoptotic signaling pathway; negative regulation of transcription by RNA polymerase II; positive regulation of ATP biosynthetic process; positive regulation of muscle contraction; positive regulation of plasminogen activation; response to virus; gluconeogenesis; glycolytic process
Cellular component: cell cortex; cell surface; cytoplasm; cytosol; extracellular exosome; extracellular region; membrane; nuclear outer membrane; nucleus; phosphopyruvate hydratase complex; plasma membrane; M band
Genetic constraint (gnomAD): Loss-of-function variants: 31 observed, 45.2 expected, observed/expected ratio (o/e) 0.69, 90% interval 0.51 to 0.93. The upper end of that interval is the gene's LOEUF score, 0.93, which puts it in group 3 of 6, group 1 being the genes least tolerant of losing a copy. Missense variants: 465 observed, 555.35 expected, observed/expected ratio (o/e) 0.84, 90% interval 0.77 to 0.9. Synonymous variants: 209 observed, 217.74 expected, observed/expected ratio (o/e) 0.96, 90% interval 0.86 to 1.08.
Homologues: Orthologues: chimpanzee ENO1 (100% identical), pig ENO1 (96% identical), guinea pig ENO1 (96% identical), mouse Eno1 (95% identical), mouse Eno1b (95% identical), rat Eno1 (95% identical), dog ENO1 (93% identical), zebrafish eno1a (90% identical), tropical clawed frog eno1 (89% identical), zebrafish eno1b (86% identical), rat Eno1-ps1 (81% identical), rabbit ENO1 (79% identical), and 3 more. Paralogues in human: ENO2 (83% identical), ENO3 (83% identical), ENO4 (25% identical).
Diseases named in the same sentence as ENO1 in open-access papers:
ENO1 is named in the same sentence as 255 diseases in open-access papers, as found by Europe PMC text mining. Sharing a sentence is not in itself a finding about the gene and the disease. The quoted sentences say what the papers report.
breast carcinoma (106 papers, 2007 to 2025). "The expression and surface localization of ENO1 were positively associated with the cancer progression, invasiveness and doxorubicin-resistance in breast cancer." (PMID 40612109, 2025). "The proteins E6AP (ubiquitin ligase E6-associated protein) and ENO1 interact predominantly in the cytoplasmic periphery of breast cancer cells." (PMID 40005870, 2025). "It has been discovered that C5ar1‐positive neutrophils, a group of neutrophils linked to the growth of breast cancer, increase BC cell glycolysis via upregulating ENO1 expression." (PMID 40919129, 2025). "Another study demonstrated that ENO1 was associated with radioresistance in breast cancer cells through an analysis of data from the GEO database." (PMID 38137461, 2023). "In SK-BR-3 breast cancer, silencing of ENO1 caused a significant decline in tumor proliferation and colony formation." (PMID 35434271, 2022). "Conversely, elevated ENO1 expression on the cell surface causes paclitaxel-treated cancer cells to be super-invasive in breast cancer cells." (PMID 35434271, 2022). "In several types of cancer, including cholangiocarcinoma, breast cancer, head and neck cancer, leukaemia, lung cancer, pancreatic cancer and melanoma, ENO1 has shown diagnostic and prognostic importance." (PMID 33184998, 2020). "Bipotent stem-cell-like cells are associated with the clinical outcome of breast cancer, that is, overexpression of regulatory genes Ybx1 and ENO1 is associated with the risk of breast cancer." (PMID 33614479, 2020). "The bipotent stem-like state correlates with clinical outcome in basal breast cancer and is characterized by overexpression of YBX1 and ENO1, two modulators of basal breast cancer risk." (PMID 31428694, 2019). "Remarkably, YBX1 and ENO1 are two transcription factors whose targets are highly enriched for breast cancer GWAS eQTLs46, thus implicating them in breast cancer risk." (PMID 31428694, 2019). "ENO1 is involved in the induction of cell death in fibroblasts and has been implicated in tumorigenicity of human breast carcinoma cells." (PMID 23711280, 2013). "Immunohistochemical analysis revealed that overexpression of ENO1 was only detected in tumor cells of canine mammary carcinoma and significantly correlated with shorter 5-year cause-specific survival." (PMID 22014164, 2011). "α-Enolase (ENO1) is a key glycolytic enzyme implicated in the development of many human cancers including breast cancer." (PMID 22014164, 2011). "In this way, the evaluation of ENO1 expression, including its subcellular location, may represent an important tool for diagnostic, and therapeutic individualization in breast cancer." (PMID 41179678, 2025). "In breast cancer, overexpression of ENO1 may be associated with lower metastasis-free survival, and poor prognosis, whereas its silencing suppresses proliferation and autophagy, while inducing apoptosis in pancreatic cells." (PMID 41179678, 2025). "ENO1 is associated with a better prognosis only in early-stage breast cancer, which may be related to the different effects of ENO1 on immune infiltration." (PMID 39337387, 2024). "Breast cancer lymphatic metastasis and ENO1 are also linked." (PMID 37810778, 2023). "Furthermore, some studies also showed that the level of ENO1 antibody was as a diagnostic or disease progression marker in lung cancer and breast cancer." (PMID 35130884, 2022). "Previous investigations report an association between in situ ENO1 overexpression and a worse clinical outcome in a variety of tumors, such as pancreatic adenocarcinoma 25, hepatocellular carcinoma 28, 42, glioma 14, breast cancer 15, and head and neck cancer." (PMID 33628097, 2021). "Further investigation is required to elucidate whether the molecular events that underlie ENO1 overexpression in canine mammary carcinoma is ER signaling machinery-associated or -dependent as proposed in human breast cancer." (PMID 22014164, 2011).
breast carcinoma (continued). "Our results suggest that ENO1 may play a predictive diagnostic role, aiding in more individualized therapeutic strategies and contributing to the advancement of precision medicine in breast cancer." (PMID 41179678, 2025). "Previous studies have demonstrated that ENO1 overexpression was positively associated with progression and poor prognosis in neuroendocrine tumors, neuroblastoma, pancreatic cancer, prostate cancer, cholangiocarcinoma, thyroid carcinoma, hepatocellular carcinoma, and breast cancer." (PMID 25887760, 2015). "After Enolase 1-transfected breast cancer cells were injected into nude mice, tumor growth significantly decreased, and tumor volume and weight both reduced." (PMID 40005870, 2025). "Inhibition of enolase 1 expression can induce senescence in breast cancer cells but can support cell survival when glutamine metabolism is inhibited by the glutaminase inhibitor BPTES(bis-2-[5 phenylacetamino-1,2, 4-thiadiazole-2-yl] ethyl sulfide)." (PMID 40865948, 2025). "C5aR1+ neutrophils stimulate the glycolytic process in breast cancer cells through exosome-mediated regulation of Enolase 1 (ENO1) m6A methylation." (PMID 40342932, 2025). "This study reveals the EMC2/USP7/ENO1/B-MYB protumorigenic axis in breast cancer and identifies EMC2 as a candidate target for PDK1/AKT inhibitory therapy." (PMID 40303285, 2025). "CPT1A facilitates glutamine-independent growth of breast cancer cells by increasing the global lysine succinylation status in cells, especially the succinylation of enolase 1 at K80/81 and K335, which inhibits enolase activity." (PMID 40865948, 2025). "(2023) pointed to the overexpression of ENO1 in molecular subtypes of breast cancer, linking this characteristic to worse prognosis and clinical outcomes." (PMID 41179678, 2025). "Neutrophils in breast cancer can mediate m6A methylation of WTAP‐dependent ENO1 to promote glycolysis in breast cancer." (PMID 39865544, 2025). "Experiments proved that CPT1A acts as an LSTase to inhibit enolase 1 enzyme activity and promote the proliferation of breast cancer cells under glutamine starvation." (PMID 40865948, 2025). "E6AP has been shown to target ENO1 for degradation, highlighting the importance of this interaction in oncological contexts, especially in breast cancer." (PMID 40005870, 2025). "In contrast, downregulation of ENO1 by specific small interfering RNA effectively restored 4-hydroxytamoxifen-induced cytotoxicity in tamoxifen resistant breast cancer cells." (PMID 40612109, 2025). "NEAT1_1 accelerates glycolytic activity in breast cancer through substrate channeling of PGK1, PGAM1, and ENO1, bringing them into close association in the cytoplasm." (PMID 40804479, 2025). "Specifically, the ERK1/2-WTAP-dependent m6A methylation modification enhances the stability of ENO1 and its glycolytic activity, thereby providing metabolic support for the proliferation and metastasis of breast cancer cells." (PMID 40342932, 2025). "ENO1 subsequently promotes breast cancer progression by stabilizing the expression of the downstream transcription factor B-MYB, which ultimately activates the PDK1/AKT/mTOR signaling pathway thereby promoting breast cancer progression." (PMID 40303285, 2025). "Availability of a small, cell-permeable molecule inhibitor of ENO1 such as ENOblock/AP-III-a4 suggests that breast cancer patients with high levels of ENO1 mRNA can be potentially targeted for treatment." (PMID 41373732, 2025). "Enolase 1 (ENO1), a glycolytic enzyme, promotes tumor progression in some tumor types, including colorectal cancer, non-small cell lung cancer, and breast cancer." (PMID 40296917, 2025). "This suggests that ENO1 contributes to the survival of breast cancer via chemoresistance while contributing to the survival of prostate cancer via angiogenesis and immune evasion." (PMID 40214422, 2025).
breast carcinoma (continued). "The prognostic potential of ITIH2 and ENO1 for mammary tumors in bitches was assessed using ROC curve analysis, which revealed limited predictive power." (PMID 40005870, 2025). "There is only a single published study on ENO1 and canine mammary tumors, and that study showed that ENO1 overexpression was detected only in canine mammary carcinoma tumor cells and significantly correlated with shorter 5-year cause-specific survival." (PMID 40005870, 2025). "This study focuses on two potential biomarkers—Inter-Alpha-Trypsin Inhibitor Heavy Chain 2 (ITIH2) and Enolase 1 (ENO1)—which have been identified in previous research as relevant to canine mammary tumors." (PMID 40005870, 2025). "Chu and colleagues (2011) examined ENO1 expression by immunohistochemical staining and evaluated its importance in canine mammary carcinoma." (PMID 39061201, 2024). "Other studies have shown that C5AR1‐positive neutrophils can also release inflammatory factors such as IL1 β, TNF α and ENO1, which are known to promote tumour progression in breast cancer." (PMID 39580709, 2024). "Studies have revealed that ENO1 promotes the occurrence and metastasis of pancreatic and breast cancers by activating (PI3K/AKT) pathway and affecting the glycolytic pathway." (PMID 39576845, 2024). "ENO1 has been demonstrated to enhance the progression of gastric cancer, lung cancer, and breast cancer." (PMID 37807062, 2023). "It is proposed that ENO1's anti-tumor action is in part mediated by CD44 which is known to promote cell proliferation in breast cancer cell lines." (PMID 37056934, 2023). "Mechanically, IL1β and TNFα secreted by C5aR1 positive neutrophils can act on the downstream ERK1/2-WTAP-ENO1 signal axis, increase the m6A modification level of ENO1 mRNA, and promote ENO1 expression and glycolysis in breast cancer cells." (PMID 37582735, 2023). "Overexpression of ENO1 was proved to be correlated with poor prognosis in various types of cancers including breast cancer, gastric cancer, bladder cancer, glioma and non-small cell lung cancer." (PMID 36614179, 2023). "For instance, extracellular Eno1 recombinant proteins are reported to suppress the metabolic activities of breast cancer cells and act as cytotoxic agents by downregulating Snail, TGFβ, and MMP9." (PMID 38250812, 2023). "UBE3A interacted with ENO1 to contribute to its ubiquitination and proteasomal degradation in breast cancer cells." (PMID 37385985, 2023). "This study presents the tumor-suppressive action of AMPK-inhibited PBMC/lymphocyte-derived CM and evaluates the role of ENO1/MSN-Mtdh regulatory axis as well as PABPC1 in suppressing the progression of breast cancer." (PMID 36923539, 2023). "Inhibition of the expression of ENO-1 by siRNA enhanced the cytotoxic effects of tamoxifen in tamoxifen-resistant breast cancer cells, rationalizing the use of ENO-1 as a drug target to reverse tamoxifen resistance in breast cancer." (PMID 36984785, 2023). "Experimentally, it was shown that ENO1 enhances radioresistance in breast cancer by regulating mitochondrial homeostasis to reduce ROS production and inhibit apoptosis." (PMID 38137461, 2023). "The expression of ENO1 in the invasion and metastasis of tumor cells was concerned by many studies with high expressions in OS, breast cancer, lung cancer, and hepatocellular carcinoma." (PMID 35547257, 2022). "Overexpression of ENO1 has been shown to enhance tamoxifen resistance in breast cancer, and promote cisplatin resistance in gastric cancer cells by stimulating glycolysis, as well as methotrexate resistance in human HT29 cells." (PMID 36620599, 2022). "ENO1 has also been found to regulate the development of various cancers, including breast cancer, lung cancer, head and neck cancers, gastric cancer, and glioma." (PMID 35805203, 2022). "As m6A methyltransferase, WTAP promotes RNA m6A methylation of ENO1 and affects the glycolysis activity of breast cancer cells, thereby affecting tumor progression and metastasis." (PMID 35251177, 2022).
breast carcinoma (continued). "The results using 4T1.2 mammary tumor cells showed that Eno1 pulled down both WT and MT CD44 proteins, indicating that extracellular Eno1 interacted with the ECM domain of CD44." (PMID 35547745, 2022). "In Stage IV breast cancer, the data show that the patients have dramatically lower levels of the ENO1 auto-antibody (P < 0.001) than healthy individuals (n = 99) or female controls (n = 49)." (PMID 34671213, 2021). "Nevertheless, after silencing the PTTG1 gene, the expression of the ENO1 downstream increased, thereby regulating the proliferation and apoptosis of breast cancer cells." (PMID 34504528, 2021). "The study indicates that the titer change of ENO1 is a key factor associating with tumor malignancy of NSCLC, SCLC and breast cancer patients." (PMID 34671213, 2021). "Chinese patients with high expression of ENO1 had poor prognosis in a variety of cancers, including breast cancer, glioma, bladder cancer, pancreatic cancer, liver cancer, gastric cancer (Chinese)." (PMID 34504528, 2021). "Collectively, our study reveals a novel subset of C5aR1-positive neutrophils that induces breast cancer glycolysis via increasing ERK1/2-WTAP-dependent m6A methylation of ENO1." (PMID 34312368, 2021). "The application of a pharmacological agent (ENOblock - AP-III-a4), an inhibitor of Eno1, suppressed the inhibitory effect of β-catenin-overexpressing iTS CM on the migration and invasion of mammary tumor cells." (PMID 34373756, 2021). "ENO1 has been shown to induce autoantibodies in patients with cholangiocarcinoma, breast cancer, head and neck cancer, leukemia, lung cancer, pancreatic cancer and melanoma." (PMID 33643901, 2020). "In breast cancer cells, ENO1 and other related proteins can reduce the expression of heat shock protein." (PMID 32013122, 2020). "The prognostic value of ENO1 mRNA expression in breast cancer patients using the Kaplan–Meier plotter database was also investigated." (PMID 31416219, 2019). "In breast cancer, increased levels of cell surface ENO-1 correlated with enhanced migration and invasion of cancer cells and these effects where abrogated by a specific peptide blocking PLG binding to ENO-1." (PMID 31106201, 2019). "While the majority of breast carcinomas displayed increased ENO-1 levels, the levels of MBP-1 were reduced with a concomitant increased in the activity of c-myc." (PMID 31106201, 2019). "Here, we investigated the functional relationship, in a cohort of breast cancer patients, between ENO1/MBP-1 expression and MMP-2 and MMP-9 activity levels in both tissues and sera." (PMID 31416219, 2019). "The concomitant expression of ENO1 (48 kDa) and MBP-1 variant (37 kDa) was evaluated in a cohort of 29 breast cancer tissues." (PMID 31416219, 2019). "Collectively, these results suggest that ENO1 is overexpressed both at the mRNA and the protein level in breast cancer tissues, and the upregulated ENO1 mRNA is correlated with a worse prognosis." (PMID 31416219, 2019). "Specifically, it has been observed that genes within the YBX1 and ENO1 regulons are strongly enriched for GWAS breast cancer eQTLs46." (PMID 31428694, 2019). "A clear association between the higher mRNA expression level of ENO1, MMP-2 and MMP-9 with a worse prognosis was already detected, suggesting that the elevated ENO1 and MMPs are promising biomarkers for breast cancer." (PMID 31416219, 2019). "It has been reported that ENO1 was up-regulated in various human cancers including gastric cancer, glioma, breast cancer, lung cancer, head and neck cancer, endometrial carcinoma, pancreatic adenocarcinoma, and Non-Hodgkin's Lymphomas (NHLs)." (PMID 28548950, 2017). "This notion is well in line with a recently published study demonstrating that caveolae-associated ANX2 along with caveolin-1 (Cav-1) are needed for the transport of cytosolic ENO-1 to the surface of breast cancer and monocytic cells." (PMID 25407528, 2014).